NF1 (neurofibromin 1)
Diseases named in the same sentence as NF1 in open-access papers (continued):
Sharing a sentence is not in itself a finding about the gene and the disease.
tumor (continued). "Expression may depend on the tumor heterogeneity, i.e., the number of cells that are actually not expressing functional NF1, and its location, since the expression profiles of NF1 and related genes are tissue-dependent." (PMID 32858845, 2020). "NF1 is a tumor suppressor gene and a negative regulator of Ras protein." (PMID 33061844, 2020). "All the NF1-related tumours show bi-allelic inactivation of the NF1 gene." (PMID 33066259, 2020). "Our findings also support the hypothesis that NF1-mediated suppression of RAS/ERK signaling is a key AIS tumor-suppressive mechanism." (PMID 31285545, 2020). "The “MET-addicted” NF1-MET tumor model is highly responsive to MET inhibition." (PMID 32245042, 2020). "This treatment showed efficacy on LGG, and targeting NF1 NBS pHGG resulted in tumor regression." (PMID 33348922, 2020). "NF1-associated symptoms and subjective tumor growth were not significantly increased in pregnant patients." (PMID 32343738, 2020). "Indeed, combined treatment with mTOR and HDAC (Histone DeACetylases) inhibitors proved to kill NF1-mutant tumours of the nervous system both in vivo and in vitro." (PMID 33066259, 2020). "The high prevalence of these tumours and their potential to transform towards malignancy as well as the loss of the SUZ12 gene included in the NF1 microdeletion region represent predisposing factors which increase the MPNST risk of patients with large NF1 deletions." (PMID 32533297, 2020). "In the 2013 “WHO Classification of tumours of soft tissue and bone”, JCS is therefore defined as the association of NOFs and NF1, but NOFs, considered for years as a distinctive feature of JCS, have also been reported in NF1 patients." (PMID 32393377, 2020). "NF1 is a tumor suppressor gene located on chromosome band 17q11.2." (PMID 32590748, 2020). "Genomic studies of NF1-derived tumors, particularly MPNSTs, have identified key features of tumor growth that could point to potential therapeutic avenues." (PMID 32098059, 2020). "Depending on the tumor type, NF1 genes may act as either an oncogene or tumor suppressor, potentially through their regulatory effects on gene expression." (PMID 33092094, 2020). "To investigate the phenotypic effects of Nf1 loss in vivo, we used the expression of phosphorylated Erk (p-Erk) as a readout for activation of Ras-mediated Erk/MAPK signaling during early stages of tumor evolution in vivo." (PMID 32699356, 2020). "Of 39 of the 51 sequenced tumours considered to represent MPNST, two were epithelioid MPNSTs and 16 were from patients exhibiting the clinical phenotype of NF‐1, a finding substantiated by detection of germline NF1 mutations in 12/16 patients." (PMID 32666581, 2020). "Conversely, a lower percentage of SOX2-positive cells was observed in the NF1-knockdown tumor." (PMID 30967630, 2019). "A series of studies elegantly showed that these cells are required to sustain tumor growth, since loss of NF1 in neuroglial progenitor cells alone does not result in gliomagenesis." (PMID 31739524, 2019). "We, therefore, explored the possibility that STX3451 and/or STX2895 could also block cell migration in NF2-null tumour cells using “wound-healing” assays as we had previously done for NF1 cells." (PMID 31730023, 2019).
tumor (continued). "Although enhancing RAS-ERK signaling during normal tumor growth conditions, NF1 deficiencies are not as dominant drivers of MAPK signaling activity as oncogenic versions of KRAS." (PMID 30858928, 2019). "Moreover, overexpression of NF1 decreased subcutaneous tumor volumes for doxorubicin‐treated PDKN1 and PDKN2 cell lines." (PMID 31036704, 2019). "Neurofibromin 1 (NF1) is a major tumor suppressor gene located on chromosome 17q11.2." (PMID 31199580, 2019). "NF1 acts as a tumor suppressor and its loss-of-function mutation results in activation of the RAS/RAF/MAPK signaling pathway, consequently contributing to tumor progression." (PMID 30263099, 2018). "While various model systems have been implemented to induce tumor development in mice, these have not proven to be representative of the complex natural history of NF1-associated tumorigenesis." (PMID 30302402, 2018). "These particular findings were confirmed by the analysis of Nf1-deficient neoplastic cells (astrocytes) by qPCR and tumor-associated microglia (non-neoplastic cells) using isolated cells and data previously acquired." (PMID 29787563, 2018). "It is possible that NF1 isoform expression and splice variation instruct tumor development, and may account for variability in genotype-phenotype correlation." (PMID 30182054, 2018). "NF-1 gene mutations can lead to dysregulation of RAS/MAP kinase and mammalian target of rapamycin (mTOR) signaling pathways which can lead to development of several types of neoplasms." (PMID 29849532, 2018). "Further elucidating the mechanisms underlying the impairment of cancer progression by tumor microenvironment cells harboring a tumor suppressor genes in the haploinsufficient state, such as NF1+/−, may translate into novel therapeutic strategies." (PMID 30479396, 2018). "Here, we show that the NF1 tumor suppressor is an additional substrate of CAPN1." (PMID 30131853, 2018). "Thus, this suggests that in both humans and mice the Nf1+/− microenvironment favors the development of benign tumors." (PMID 30479396, 2018). "The NF1 group was differentiated for facial tumor type and localization." (PMID 29670726, 2018). "As we progress in our quest to decipher the biology of cNF, it remains important to compare and contrast cNF and pNF in terms of cellular origin, NF1 genotype and modifiers, cellular composition, and the effect of tumor microenvironment, as well as the effects of sex hormones." (PMID 29987131, 2018). "NF1 somatic mutations specifically and MAPK pathway alterations overall are worthy of further exploration as potential prognostic markers as these were significantly more likely in patient tumor samples which had recurred." (PMID 30345349, 2018). "It is interesting to note that the rate of tumor regression in the Nf1 tumors after estrogen ablation was remarkably rapid and included all Nf1 tumors regardless of mutation (PS or IF)." (PMID 30182054, 2018). "However, despite their uniqueness, all Nf1 murine optic gliomas examined share a 25-gene expression signature that distinguishes tumor tissue from normal optic nerve." (PMID 28881745, 2017). "In the current study, we employed whole-tumor RNA-sequencing and mathematical deconvolution strategies using preclinical mouse models of Nf1 optic glioma to characterize the tumor ecosystem as an aggregate gene expression pattern distinct from the healthy optic nerve." (PMID 28881745, 2017). "Consequently, a readilyidentifiable subgroup of NF1 patients with germline NF1 microdeletions is likely to exhibit an extremely high burden ofinternal tumours." (PMID 28213670, 2017). "Both histological types can be present in the same tumor mass in patients with NF1." (PMID 29138703, 2017). "It is possible that NK cells in Nf1+/− mice may be compensated for by reduced ERK phosphorylation and rescue of MAPK/ERK signaling in the tumor microenvironment; thus, Nf1+/− mice would exhibit an increase in antitumor immunity and have enhanced survival." (PMID 29354122, 2017).
tumor (continued). "NF1 is a tumor suppressor gene encoding a direct negative regulator of RAS, which cooperates with mutated BRAF in melanomagenesis by preventing oncogene‐induced senescence." (PMID 28267273, 2017). "NF1 inactivation may alter the transcriptional landscape of a tumor and allow a machine learning classifier to detect which tumors will benefit from synthetic lethal molecules." (PMID 28166733, 2017). "Further, low or negative NF1 protein expression was associated with T stage (P<0.05) and tumor node metastasis (P<0.001)." (PMID 29137312, 2017). "Further analysis of the NF1 deletion-bearing tumours revealed significantly higher levels of active RAS, indicating that RAS signal transduction pathway dysregulation, through NF1 loss, may be responsible for driving malignancy in these cells." (PMID 28637487, 2017). "The highest number of differentially methylated probes were detected in tumours with NF1-mutations (1651 probes) followed by those without known mutations (1184 probes), those with RET-mutations (432 probes) and those with VHL-mutations (339 probes)." (PMID 28327598, 2017). "At present, NF1 is classified a tumour suppressor gene disease." (PMID 28401031, 2017). "There were three pairs of genes that were mutated in a mutually exclusive pattern in tumor samples (n = 412): BRAF and NRAS mutations (Bonferroni adjusted p-value < 0.05), BRAF and NF1 mutations (Bonferroni adjusted p-value < 0.05), and NRAS and PTEN mutations (Bonferroni adjusted p-value < 0.05)." (PMID 29383127, 2017). "These resections rely on magnetic resonance imaging (MRI) to visualize tumor location and infiltration, but even in the setting of an established NF-1 diagnosis, additional imaging can be beneficial in ruling out more precarious tumors and optimizing surgical outcomes." (PMID 29147633, 2017). "Similarly, the miR-193b was also reported to modulate cell proliferation, migration, and invasion, and downregulation of miR-193b contributes to enhanced tumor progression and invasion through its target gene-neurofibromin 1(NF1)." (PMID 27582688, 2016). "Tumor penetrance in the progeny of this cross varied widely depending on the nf1 genotype." (PMID 27130733, 2016). "In addition, all neoplasms harbored mutations that directly or indirectly affected either the regulation or activation of the PI3K pathway (PIK3CA, NF1, INPP5B and GSK3B)." (PMID 27057633, 2016). "In our set of samples, Tumor #1 and Tumor #3 carried mutations in PIK3CA, with variant allele frequencies of 38% and 26%, and Tumor #4 harbored an NF1 mutation, which might activate the PI3K signaling pathway." (PMID 27057633, 2016). "The NF1 gene on chromosome 17q11.2 is a classic tumor suppressor gene." (PMID 26432421, 2015). "Simultaneous activation of the KRAS oncogene together with inactivation of NF1 tumour suppressor could be lethal to cell survival, and hence these two events rarely co-occur (p-value = 0.001)." (PMID 26427375, 2015). "It is perhaps not surprising to find NF1 gene inactivation in a sporadic wild-type GIST, as NF1 somatic mutations have been identified in a number of non-NF1-associated tumor types." (PMID 26555092, 2015). "C2A tumours are mainly driven by RET, NF1 and HRAS mutations." (PMID 25625332, 2015). "Three tumours contained mutations in ERBB2/RAS/RAF/MEK pathway members or regulators: an ARAF mutation in combination with a NCK1 mutation, a PAK1 mutation in combination with a NF1 mutation, and an ERBB2 mutation in combination with a TSC1 mutation." (PMID 26506417, 2015). "We assessed cell proliferation to determine whether similar to the MEFs and Nf1 mutant tumor cell lines Grb10 expression suppressed cell proliferation of Ras-transformed cells." (PMID 26000738, 2015).
tumor (continued). "Grb10-overexpressing V16HRas-transformed human astrocytes demonstrated sustained phosphorylated ERK, in contrast to the Nf1 mutant tumor cell line 881, which similar to the 989 tumor cell line showed significantly reduced MAPK signaling and slightly reduced Akt phosphorylation." (PMID 26000738, 2015). "Specifically, Clusters C1A and C1B, comprising SDHx- and VHL-mutated tumours, respectively, display a pseudohypoxic signature, whereas Cluster C2A, corresponding to RET-, NF1- and TMEM127-mutated tumours, displays activation of the RAS/mitogen-activated protein kinase (MAPK) signaling pathway." (PMID 25625332, 2015). "Likewise, mutations in NF1, a suppressor of RAS activity, were negatively associated with EGFR mutations in GBM, a tumor type in which activating deletions in the extracellular domain of EGFR are typically found." (PMID 26047463, 2015). "This function had been identified in an Nf1 mutant tumor cell line." (PMID 26000738, 2015). "Thus NF1, VHL, RET, and MAX germline and somatic mutations have been reported in 3–25%, 13–9%, 5–5%, and 1–3% of tumours, respectively." (PMID 25883647, 2015). "Grb10 restoration significantly decreased pERK levels and proliferation in these tumor cells, indicating that Grb10-mediated growth suppression does not require Nf1 loss." (PMID 26000738, 2015). "Analysis of primary tumor samples identified 19 tumors from Nf1+/- mice in which Nf1 and Grb10 status could be co-determined." (PMID 26000738, 2015). "This difference between HEK293 cells and our Nf1 mutant tumor cells may reflect the possibility that a Grb10-mediated negative feedback loop acting upon mTOR also requires fully intact Ras regulation, such as neurofibromin." (PMID 26000738, 2015). "However, this has also recently been the case for another RasGAP molecules, neurofibromin (or NF1), which is also a known tumor suppressor." (PMID 24912918, 2014). "The gene responsible for NF1 is located on chromosome 17q11.2, and its protein product, neurofibromin, is ubiquitously expressed at high levels in the nervous system, and functions as a tumor suppressor." (PMID 24678641, 2014). "The NF1 gene is a classic tumour suppressor gene on chromosome 17." (PMID 25026295, 2014). "Additionally, the catecholamine output observed in H-RAS mutated tumours resemble that of RET and NF1." (PMID 24466223, 2014). "Analysis failed due to corrupted data in two cases, one SDHB and one NF1-related tumour." (PMID 24466223, 2014). "Furthermore, MLK3 was reported to be important for the proliferation of tumor cells, bearing either oncogenic KRAS or neurofibromatosis-1 (NF1) or NF2 inactivating mutations." (PMID 24628919, 2014). "Haploinsufficiency for the NF1 tumour suppressor may have functional consequences, such as increased astrocyte proliferation and augmentation of angiogenesis in Nf1+/− heterozygous mouse models." (PMID 25026295, 2014). "Although the number of tumors per animal in the NF1-associated mouse model was not reduced, tumor grade was much lower with Everolimus treatment." (PMID 24681606, 2014). "Hyperactivation of the signaling pathways that govern NF1-associated tumor growth can result from growth factors or cytokines produced by non-neoplastic cells in the tumor microenvironment." (PMID 25243094, 2014). "There was evidence of Ras pathway activation in these tumours and cell lines with NF1 defects, in the absence of KRAS or BRAF mutations." (PMID 25026295, 2014). "According to our knowledge, the association between this type of tumor and NF1 gene mutation has never been described." (PMID 24708790, 2014). "The frequency of somatic NF1 aberrations in sporadic tumours is increasingly recognized." (PMID 25026295, 2014).
tumor (continued). "Our patient had a tumor huge in size compared to those of previous reports with multiple pleural nodules suggesting metastasis at diagnosis, which indicates delayed diagnosis despite her NF1 stigmata." (PMID 24971186, 2014). "Factors that influence survival include tumor size, location, and presence of NF1." (PMID 24191220, 2013). "NF1, a tumor suppressor involved in gliomagenesis, has been reported to modulate cell motility." (PMID 23185366, 2012). "We also found that women with NF1 have greater tumor burden, on average, than men." (PMID 22558206, 2012). "The extent of LOH in the NF1 gene was also found to vary between sections of the same tumor." (PMID 23244685, 2012). "The NF1 gene encodes a protein known as neurofibromin; its loss may constitutively activate the RAS signaling pathway and contribute to tumor development." (PMID 22778956, 2012). "Thus, some sections displayed LOH over the entire NF1 gene and surrounding regions, whereas other sections of the same tumor only exhibited LOH within a portion of the NF1 gene." (PMID 23244685, 2012). "However, they were considered to bear a deletion in the NF1 locus, based in the similarity with other tumor samples bearing the same localized AI (only affecting the NF1 gene and surrounding regions)." (PMID 22916147, 2012). "Neurofibromin-1 (NF1) is a tumor suppressor and a negative regulator of RAS." (PMID 22509804, 2012). "Since the mTOR pathway is already activated in NF1-associated tumours due to a lack of NF1, it is likely that further activation of the Akt/mTOR pathway due to Pten loss promotes tumour progression in this setting." (PMID 23139750, 2012). "Interestingly, SOX9 was also recently found to be expressed in NF1-related tumours, where it supports cellular survival." (PMID 21726432, 2011). "Notably, many of the qPCR-ratios obtained for Cdkn2a and Nf1 were consistent with losses throughout the tumor." (PMID 21533183, 2011). "On the other hand, the recombination crossovers of a few dNFs could be located really close to the NF1 gene, even closer than in tumor P103-5N." (PMID 21031597, 2011). "In mice haploinsufficiency of NF1 fosters a permissive tumorigenic environment for the development of neurofibromas, optic nerve gliomas and blood vessels, suggesting a role for haploinsufficiency itself in tumor formation." (PMID 20307317, 2010). "We report here a pair of NF1 MZ twins with remarkable concordance in their tumour phenotype." (PMID 20687928, 2010). "We hypothesized that the genetic effects of NF1-haploinsufficiency may be discerned by comparison of genome-wide transcriptional profiling in somatic, non-tumor cells (LCLs) from NF1-affected and -unaffected individuals." (PMID 20307317, 2010). "The NF-1 gene is a tumor suppressor gene mapping to chromosome 17q11.2." (PMID 20219130, 2010). "We hypothesized that the genetic effects of NF1-haploinsufficiency may be discerned by comparison of genome-wide transcriptional profiling in somatic, non-tumor cells from NF1-affected and -unaffected individuals." (PMID 20307317, 2010). "Moreover, tumor derived human Schwann cells from NF1 patients can stimulate angiogenesis and there is evidence for enhanced expression of angiogenic factors in NF1 deficient cells A recent study showed VEGF expression in all MPNST analyzed (n = 22)." (PMID 20686603, 2010). "Nf1 is a tumor suppressor that regulates normal hematopoiesis." (PMID 20098702, 2010). "A recent study employing gene expression profiling of NF1-associated and sporadic pilocytic and pilomyxoid astrocytomas identified aldehyde dehydrogenase 1 family member L1 (ALDH1L1) as an underexpressed candidate biomarker in more aggressive tumor subtypes." (PMID 19333441, 2009). "The observed tumor rebound following treatment cessation reinforces the importance of uninterrupted therapy in achieving sustained tumor control and raises key questions regarding the long-term management of NF1-PNs in patients facing financial or logistical barriers to care." (PMID 40271285, 2025).